PAX6 (paired box 6)
Diseases named in the same sentence as PAX6 in open-access papers (continued):
Sharing a sentence is not in itself a finding about the gene and the disease.
neurodevelopmental disorder (9 papers, 2015 to 2025). A behavioral and cognitive disorder with onset during the developmental period that involves impaired or aberrant development of intellectual, motor, or social functions. "Mutations in the highly conserved Pax6 transcription factor have been implicated in neurodevelopmental disorders and behavioral abnormalities, yet the mechanistic basis of the latter remain poorly understood." (PMID 39902612, 2025). "We examined the molecular composition of almost a trillion excitatory synapses on a brain-wide scale between birth and adulthood in mice carrying a mutation in the homeobox transcription factor Pax6, a neurodevelopmental disorder model." (PMID 36369219, 2022). "Another interesting gene downstream of Pax6 is Fmr1, a causative gene for fragile X syndrome, one of the neurodevelopmental disorders." (PMID 35682795, 2022). "Additional evidence for the involvement of the human PAX6 gene in neurodevelopmental disorders comes from a genome-wide association study (GWAS) of ASD patients." (PMID 35682795, 2022). "PAX6 exert high level of control of cortical development, and its mutation or deletion from developing brain caused major brain effects and neurodevelopmental disorders." (PMID 36313423, 2022). "Patients with mutations in the PAX6 gene may exhibit symptoms of neurodevelopmental disorders, including ASD." (PMID 35682795, 2022). "We also review the pathological effects of PAX6 mutations in human neurodevelopmental disorders." (PMID 25805971, 2015). "Pax6 is one of a relatively small group of transcription factors that exert high-level control of cortical development, and whose mutation or deletion from developing embryos causes major brain defects and a wide range of neurodevelopmental disorders." (PMID 25805971, 2015). "Our studies along with others have shown that Pax6 expression levels are crucial for its functions such as regulating progenitor cell proliferation and differentiation, and that mutations affecting Pax6 protein levels cause neurodevelopmental disorders in both humans and mice." (PMID 25805971, 2015). "Furthermore, mutations in PAX6 have been implicated in neurodevelopmental disorders such as autism spectrum disorder (ASD), with several patients exhibiting not only eye phenotypes but also behavioral issues like cognitive dysfunction, linguistic impairment, social defects, and motor impairment." (PMID 39902612, 2025). "Our study adds to the growing body of evidence on how Pax6 haploinsufficiency affects animal behavior, particularly in the context of neurodevelopmental disorders such as ASD and other conditions characterized by social and sensory processing abnormalities." (PMID 39902612, 2025). "Pax6 is expressed in NSCs at all stages of embryonic, postnatal, and adult neurogenesis (see “Pax6 in neurogenesis” and “Pax6 in Relation to Neurodevelopmental Disorders”)." (PMID 35682795, 2022). "In this review article, we would like to focus on the role of Pax6 in brain development, taking neurodevelopmental disorders into account." (PMID 35682795, 2022). "Rodents that lack the Pax6 gene exhibit diverse neural phenotypes, which might lead to a better understanding of human pathology and neurodevelopmental disorders." (PMID 35682795, 2022). "Since Pax6 mutant rodents exhibit diverse neurodevelopmental phenotypes, they could be used as a tool to elucidate the human pathology of neurodevelopmental disorders." (PMID 35682795, 2022). "Therefore, we hypothesized a role of Pax6 in animal behavior and in neurodevelopmental abnormalities such as those characterizing ASD and related neurodevelopmental disorders." (PMID 27855195, 2016). "As far as we know, only 14 cases were found to carry genomic microdeletion encompassing PAX6 or its regulatory region but not WT1 to date, and only one of them displayed neurodevelopmental disorders." (PMID 25628759, 2015).
neurological disorders (8 papers, 2013 to 2025). "Neurological disorders presented in individuals with PAX6 mutations can be explained by the PAX6 expression pattern and outcome from animal model research." (PMID 25628759, 2015). "Moreover, patients with PAX6 mutations demonstrate phenotypes that match age-associated neurological disorders." (PMID 32046281, 2020). "Consequently, a number of mouse and human developmental defects and neurological disorders have been attributed to mutations in Pax6/PAX6 genes." (PMID 23342162, 2013). "The proximity of the Paupar gene to Pax6 suggested to us that it may be involved in the spatiotemporal control of Pax6 expression and hence that it may be important for nervous system development and neurological disease." (PMID 24488179, 2014).
eye disorder (2 papers, 2012 to 2020). A non-neoplastic or neoplastic disorder that affects the eye. "Thus, due to the important role that NR2E1 plays during eye development, we hypothesize that NR2E1 may be involved in human eye disorders impacting a wide range of eye structures whose development depend on NR2E1 genetic interactors such as PAX2 and PAX6." (PMID 23213277, 2012).
neurodegenerative disease (2 papers, 2016 to 2017). A disorder of the central nervous system characterized by gradual and progressive loss of neural tissue and neurologic function. "Modulation of PAX6 might in turn offer novel avenues for the treatment of neurodegenerative diseases." (PMID 27231702, 2016). "Thus, our data here may imply that the BAF45D may have significant implications for contribute to PAX6 expression, which may have significant implications for treatment of neurodegenerative diseases." (PMID 29163067, 2017).
psychiatric disorder (2 papers, 2011 to 2013). A disorder characterized by behavioral and/or psychological abnormalities, often accompanied by physical symptoms. "Furthermore, AA ameliorates the prepulse inhibition relevant to psychiatric disorder models, such as methylazoxymethanol-treated rats and Pax6 knockout rats, through augmented postnatal neurogenesis." (PMID 24137238, 2013).
retinal disorder (2 papers, 2016 to 2025). Any disease or disorder of the retina. "We addressed whether impairment of retinal regeneration by Pax6 KD in RPE cells resulted in the appearance of symptoms of RPE-mediated retinal disorders." (PMID 27640672, 2016). "Understanding RAX2’s interactions with key developmental genes like PAX6 and SOX2 is crucial for advancing gene therapy approaches for retinal disorders." (PMID 40538981, 2025).
autosomal dominant inherited disorder (1 paper, 2022). "Pax6 haploinsufficiency in mice results in abnormal eye and nasal development and causes a range of brain defects; whilst mutations affecting PAX6 expression and function in humans cause anirida, an autosomal dominant inherited disorder characterized by a complete or partial absence of the iris." (PMID 35709096, 2022).
endocrine neoplasms (1 paper, 2022). "When using older, polyclonal preparations, endocrine neoplasms (pancreatic islet cell tumors and gastrointestinal tract carcinoids) are often positive for PAX8; however, cross-reactivity with PAX6 is clarifying." (PMID 36428491, 2022).
metabolic disease (1 paper, 2023). A congenital disorder (due to inherited enzyme abnormality) or acquired (due to failure of a metabolically important organ) disorder resulting from an abnormal metabolic process. "In line with our findings, numerous neurodevelopmental, ocular, oral, and metabolic diseases have been linked to PAX6 deficiency, mutations, and genetic variants." (PMID 37834287, 2023).
peripheral neuropathy (1 paper, 2022). A disorder affecting the peripheral nervous system. "All of these TFs have previously been linked to neurogenesis or neuronal differentiation; most interestingly, the top two identified TFs, PAX6 and EBF2, have been shown to be associated with peripheral neuropathy." (PMID 35884461, 2022).
PAX6 also shares sentences with these, for which no sentence is quoted: optic nerve hypoplasia (8 papers); achromatopsia (5); aniridia syndrome (5); autism spectrum disorder (5); corneal degeneration (4); genetic disorder (4); morning glory disc anomaly (4); Retinal dystrophy (4); anterior segment dysgenesis (3); cognitive disorder (3); hepatocellular carcinoma (3); Anosmia (2); cerebellar ataxia (2); cervical carcinoma (2); Chorioretinal coloboma (2); deafness (2); ependymoma (2); fibrosis (2); Gestational Diabetes Mellitus (2); immune dysfunction (2); Impaired glucose tolerance (2); Insulin resistance (2); kidney cancer (2); maturity-onset diabetes of the young type 4 (2); Microcornea (2); multiple myeloma (2); myopathy (2); optic atrophy (2); pancreatic ductal adenocarcinoma (2); Photophobia (2).
A further 96 diseases each share a sentence with PAX6 in 2 papers or fewer.